EGFR (epidermal growth factor receptor)
Diseases named in the same sentence as EGFR in open-access papers (continued):
Sharing a sentence is not in itself a finding about the gene and the disease.
tumor (continued). "An EGFR targeting the antibody cetuximab showed antagonistic activity by inhibiting the activation of RTKs, which in turn inhibited the tumor malignancy." (PMID 33321953, 2020). "This is in agreement with studies conducted with EGFR-positive patients and highlights that the ctDNA level likely acts as a surrogate measure for the overall tumor burden." (PMID 32290439, 2020). "Consistent with EGFR polysomy and EGFR expression, the HCI-010 model was distinguished by the greatest proportion of tumor cells with ≥ 4 EGFR per cell (~ 26%)." (PMID 33256808, 2020). "The authors showed that adrenaline activates β2-AR on NSCLC cells, which cooperatively signals with mutant EGFR to induce IL-6 expression through the tumor suppressor, liver kinase B1 (LKB1)." (PMID 33142779, 2020). "EGFR overexpression in certain cancer cells promoted tumor development and metastasis, and EGFR is the marker for poor cancer prognosis." (PMID 33023595, 2020). "Both cannabinoids are known to inhibit the EGFR pathway, which modulates the proliferation of tumor cells." (PMID 32049991, 2020). "EGFR is a member of the type I tyrosine kinase receptor family, has intrinsic tyrosine-kinase activity and plays an important role in tumour development." (PMID 32103127, 2020). "Significant copy number alterations of CCND1 and EGFR correlate with clinical stage, tumor differentiation, and lymph node metastasis in oral squamous cell carcinoma (OSCC)." (PMID 33317149, 2020). "These mice also had different DC subtypes in their draining lymph nodes, that partially lost their ability to stimulate proliferation of naive T cells, compared to mice with EGFR wild-type tumours." (PMID 33143170, 2020). "Transporting via the Golgi apparatus and endoplasmic reticulum to the nucleus allows EGFR to act as a transcriptional regulator involved in cell proliferation, tumor progression, DNA repair, and chemo- and radioresistance." (PMID 32377505, 2020). "Programmed cell death ligand 1 (PD-L1) expressed on tumor tissues is a vital molecule for immune suppression and its impact on the response to epidermal growth factor receptor tyrosine kinase inhibitors (EGFR-TKIs) has been reported." (PMID 32983977, 2020). "The amplification of EGFR and PDGFRA genes are often considered to be among the key mutations driving oncogenesis and tumour growth." (PMID 33120534, 2020). "The remarkable fluorescence signal from EGFR-positive cells, as well as in vivo tumor tissues, implied the potential of using this system for bioimaging in real surgery." (PMID 34691533, 2020). "In this study, we demonstrated that the tumour tissues of NPC patients with distant metastasis presented increased EGFR expression and decreased ROS levels." (PMID 33304472, 2020). "Unlike the uptake behavior observed for single agents alone, the RA estimates in the EGFR(+) tumor line revealed increasing separation between treated and untreated animals as time progressed." (PMID 33042280, 2020). "Another specific NIRF tracer, ABY-029, outperformed 5-ALA in detecting the tumor margin of EGFR-positive tumors and has the potential to enhance fluorescence-guided surgery." (PMID 33193439, 2020). "EGFR expression was significantly more frequent in castration-resistant bone metastases, when compared to its distribution in primary tumours (n = 39 vs. n = 1841, Chi2 = 11.543, p = 0.009)." (PMID 32901137, 2020). "High EGFR and PTEN mutation are common in GBM, and actively participate in promoting tumor progression." (PMID 32984316, 2020). "By screening 79 commercially available natural products, we found that the natural compound deguelin exhibited a profound anti-tumor effect on NSCLC via directly down-regulating of EGFR-signaling pathway." (PMID 32081857, 2020). "An ex vivo human tumor assay has shown distinct patterns of EGFR trafficking in SCC, correlating with therapeutic outcomes." (PMID 32516941, 2020).
tumor (continued). "Three times more GE11 EVs containing let-7a were detected in the cell tumour, suggesting EV targeting to tumour expressed EGFR, which significantly suppressed tumour growth compared to control EVs." (PMID 33143170, 2020). "In this work, we explored PD-L1-CAR T-cell therapy as an alternative treatment approach for NSCLC with PD-L1high and EGFR mutant phenotypes (for example, PD-L1 expression assessed to be ≥50% tumor proportion score)." (PMID 32792499, 2020). "Overexpression of EGFR is thought to play an important role in proliferation and survival of tumor cells in a variety of cancers." (PMID 32413049, 2020). "Unlike erlotinib and gefitinib, afatinib has a relatively high affinity to wild-type EGFR, resulting in increased side effects such as diarrhea or skin rash." (PMID 33187135, 2020). "Surprisingly, after cisplatin treatment, an increase in EGFR expression was detected in all analyzed spheroids solely comprising tumor cells." (PMID 33353547, 2020). "Poziotinib failed to meet its primary endpoint (ORR 14.8%), but induced tumor reduction in 65% of NSCLC patients with EGFR exon 20 insertion mutants in a phase II trial." (PMID 33109256, 2020). "For example, the reduced EGFR signaling pathways were predicted to result in reduced tissue invasion, tumor growth, tumor metastasis, G0-G1 phase transition, and gene expression." (PMID 32528898, 2020). "It has been reported that tumour cell microenvironment stiffness regulates tumour development by interacting with EGFR-dependent signalling in glioma." (PMID 32999349, 2020). "Yang’s group built a nanofiber membrane-supported lung chip and evaluated the toxicity of gefitinib, an anti-tumor drug targeting epidermal growth factor receptor (EGFR)." (PMID 32260191, 2020). "DAB389EGF was cytotoxic for various EGFR-expressing tumor cell lines with IC50s values as low as 0.1 pM." (PMID 32957689, 2020). "The NCCN Guidelines Panel has laid down a consensus statement with respect to selection of anti-EGFR antibodies and tumor sidedness in the treatment of first line metastatic CRC." (PMID 32612957, 2020). "In the presence of EGFR inhibitors, the tumor cells respond with MET amplification, which allows the maintenance of hyperactivated cancer pathways, leading to tumor progression despite EGFR TKI treatment." (PMID 33153004, 2020). "SNVs present with allele frequency of ≤ 5% (rare SNVs) occur frequently in genes commonly mutated during cancer (for example, EGFR, KRAS, PIK3CA, and BRAF), and can provide insight into the dynamics of subclonal tumour populations." (PMID 32024475, 2020). "We next examined the role of β-catenin regulation by PFKP Y64 phosphorylation in the EGFR activation-induced tumor cell proliferation." (PMID 32195176, 2020). "These tumor cells further exhibit overexpressed growth factors and receptors, such as the transforming growth factor alpha (TGFA) and the epidermal growth factor receptor (EGFR) based on mutations." (PMID 31952211, 2020). "The coexistence of such alterations potentially shaped tumor responses to different EGFR TKI treatments." (PMID 32412152, 2020). "In a preclinical study, taking tumor bearing mice treated with anti-EGFR-guided LIGHT fusion protein into account, the study illustrated that the activation of lymphotoxin β-receptor induced production of chemokines which led to extensive T cell recruitment." (PMID 32793604, 2020). "Immunofluorescence analysis revealed that the level of YB-1 phosphorylation correlated with enhanced phosphorylation of ERK1/2 and the expression of EGFR in tumor tissues obtained from all of the 6 patients analyzed." (PMID 33003386, 2020). "In fact, NHERF1 has also been suggested to connect with tumor sensitivity to drugs targeting EGFR, MRP4 or MRP2." (PMID 32164629, 2020).
tumor (continued). "In fact, EGFR-mutant cancer cells tend to have a lower tumor mutational burden (TMB), defined as the total number of nonsynonymous mutations per coding area of a tumor genome (Mut/Mb), and to be less immunogenic compared to EGFR wild-type tumors." (PMID 33114576, 2020). "Although a link between intrinsic sensitivity to EGFR TKIs and tumor E-cadherin expression has been proposed, the direct role of E-cadherin loss in acquisition of resistance to this class of drugs is not universally agreed upon." (PMID 32292420, 2020). "Immunohistochemistry staining of the tumor tissues indicated intense expression of EGFR in the control untreated as well as 5-FU and 5FU-SLN4 treated tissues." (PMID 33046724, 2020). "It was observed that tumor cells demonstrate abnormally high EGFR activity and enhanced sensitivity to their ligands and the progression of tumor." (PMID 33066157, 2020). "In particular, in MMEC, the EGFR inhibitor erlotinib reduced new blood vessel formation and prevented tumor plasma cell growth in vitro and in vivo." (PMID 31936715, 2020). "The three TNBC cell lines and the MCF7 cell line were used to investigate the anti‐tumor activity of the EGFR‐CAR NK cells in this study." (PMID 32592435, 2020). "When loaded in extracellular vesicles (EVs), EGFR is one of the key proteins involved in the transfer of information between parental cancer and bystander cells in the tumour microenvironment." (PMID 33302515, 2020). "In summary, EGFR/ALK co-alterations can define a specific subgroup with tumor heterogeneity and diverse responses." (PMID 33363040, 2020). "For instance, similar to EGFR TKI-resistant tumor cells, normal lung fibroblasts express high levels of FGFR and PDGFR, indicating the critical importance of these growth factor signals in survival of mesenchymal cells." (PMID 32292420, 2020). "CAFs contribute to the formation and maintenance of the tumor microenvironment in cooperation with tumor cells by activating several signaling cascades including the EGFR, JAK/STAT, TGF-β, and Wnt pathways." (PMID 32546182, 2020). "Immunostaining of mouse tumor spheroids isolated from ascite, confirmed that EGF was specifically detected in TAMs that were surrounded by EGFR+ tumor cells." (PMID 33194645, 2020). "In October 2017, polymerase chain reaction (PCR) test of the tumor showed EGFR exon 19del, but targeted therapy was refused at the time of genotyping." (PMID 32656988, 2020). "Inherbin3 has exhibited the reduction of the EGFR signaling in tumor cells and the suppression of tumor growth in vivo via targeting EGFR and inhibits the EGFR phosphorylation." (PMID 32001707, 2020). "There was less pT654 EGFR in the 67NR tumor lysates, whereas the 4T1 tumors showed higher expression of pT654 EGFR." (PMID 31597954, 2020). "EGFR activation has been reported to be induced by multiple sources from tumor microenvironments, including tissue-resident myofibroblasts, bile acids (BA’s), secreted molecules, and cellular components." (PMID 32708604, 2020). "According to PET experiments in vivo, the increased avidity of the bivalent α-EGFR-EGFR TM improves the enrichment at the tumor site." (PMID 33101285, 2020). "MSN-AP with EV EGFR targeting ability inhibited lung-specific metastases and eliminated oncogenic EVs from mice bearing A549 cell tumours." (PMID 33143170, 2020). "Previous research has shown that KIAA1199 was able to stabilize the EGFR protein and facilitate EGFR phosphorylation to promote tumor survival and migration." (PMID 32519472, 2020). "Thus, our data suggest that sampling either the primary (pre- or posttherapeutical tumor tissue) or metastatic lesion may be valid for the initial evaluation of KRAS mutation status for predicting the response to anti-EGFR treatment and guiding clinical decisions." (PMID 33002027, 2020).
tumor (continued). "Tumor erlotinib and sunitinib concentrations were consistent with small sample-sized studies suggesting 4–20× higher concentrations of (mostly EGFR) tyrosine kinase inhibitors in tumor than in plasma." (PMID 32024067, 2020). "Oncogenic signalling reprograms the metabolism by shifting tumour cells to high glycolysis and lactate production, which, once extruded into the tumour microenvironment is uptaken by other tumour cells and causes immune suppression, an effect that could be demonstrated also for EGFR." (PMID 33302515, 2020). "The EGFR pathway is thought to have a role in the acquisition of resistance to anti-VEGF therapy, and treatment with anti-EGFR can select for tumour cell subpopulations with increased angiogenic potential." (PMID 32937961, 2020). "Along the same lines, following EGF stimulation a CXCR7/ACKR3-mediated process of EGFR activation was revealed (possibly through β-arrestin scaffold), leading to increased tumor cell proliferation." (PMID 32582148, 2020). "Ablation of EGFR by CRISPR/Cas9 significantly restrained tumor cell growth and activated the MAPK (pERK1/2) pathway." (PMID 32413049, 2020). "The anti-tumor effect mainly relate with the regulation of cell cycle, inhibition of the EGFR-induced cell growth and the EMT process." (PMID 33282744, 2020). "ADAM17, whose expression is in turn regulated by miRNA-145, enhances transforming growth factor-α (TGFα) and epidermal growth factor receptor (EGFR) expression, thus contributing to tumor growth and invasiveness." (PMID 32560347, 2020). "The miR-16 mimics were delivered intravenously using EnGeneIC delivery vehicle (EDV) packaging and were conjugated with an EGFR-targeting antibody to facilitate targeting to the tumor site." (PMID 32733559, 2020). "Macrophages also help tumor cells enter blood vessels; however, the inactivation of EGFR signaling blocks this process." (PMID 32883032, 2020). "Tumour material of EGFR TKI -resistant patients was examined for histological transformation and genetic mutations." (PMID 32397977, 2020). "The results revealed that once-daily dosing of osimertinib only delayed in vivo tumor development in the HCC827, H3255, and H1975 xenografts which harbored EGFR activating mutation." (PMID 32276600, 2020). "Via interactions with signaling molecules, PGs cooperate with ECM proteins and cell proliferation-related signaling events, including NF-κB and EGFR signaling pathways, to regulate tumor growth." (PMID 32825245, 2020). "In GBM, poor responses can be due to molecular heterogeneity where the tumor often includes cells with either EGFRvIII or wt EGFR expression." (PMID 32957689, 2020). "Overall, the data across many studies using a variety of modern methods demonstrate sensitivities for EGFR alterations assessed in liquid biopsy versus tumor tissue to be in the 70–85% range in patients with metastatic disease." (PMID 32596507, 2020). "Genetic testing in GFAP CTC-DNA by sanger sequencing, q-PCR and NGS methods indicated that the isolated CTCs (GFAP+/EGFR+) are the related tumor cell." (PMID 33208163, 2020). "Targeted therapies consist of anti-tumor angiogenesis, anti-EGFR therapy, tumor immunoregulatory inhibitors, anti-BRAF therapy, and anti-HER-2 therapy." (PMID 33153437, 2020). "Chou and colleagues found that with the overexpression of miR-7, a miRNA induced by EGFR, demonstrated an increase in cell proliferation and tumor growth rate through the Ras/ERK/Myc pathway." (PMID 32316322, 2020). "We found that both β-catenin and RAS, as well as epidermal growth factor receptor (EGFR), are overexpressed and correlated with one another in tumor tissues of TNBC patients." (PMID 32457491, 2020). "Epigenetic reprogramming in EGFR‐activated GBM has recently been suggested to downregulate the expression of tumour suppressor genes." (PMID 31993801, 2020).
tumor (continued). "Loss of dependence on signalling initiated by HER2–HER2 homodimers is not substantiated as a resistance mechanism by clinical or experimental studies, and the impact of EGFR expression and tumour immunological status requires further investigation." (PMID 31839676, 2020). "Our study was designed to evaluate the sensitivity of direct reflectance scanning for the detection of tumor cells in tissue and excision borders in histological sections using anti-EGFR-conjugated GNPs." (PMID 31963462, 2020). "Immunohistochemistry analysis showed that ASK120067 significantly inhibited the phosphorylation of EGFR L858R/T790M in the tumor tissue of the PDX model after 21 days of treatment." (PMID 32404161, 2020). "Deregulated EGFR results in increased signaling activity that promotes tumor phenotypes, such as invasion, metastasis, angiogenesis, and proliferation." (PMID 33182254, 2020). "Additional primary tumor markers found to associate with BCBM progression by more than one study included Ki67, EGFR, FOXC1 and CK5/6." (PMID 32110283, 2020). "Significantly lower methylation was recorded in the G0-tumor free control samples (14.4%; n = 7) as well as wildtype tumor samples (22.8%; n = 78) compared to EGFR/KRAS mutant samples (28.6%; n= 39) (p = 0.050 and p = 0.046; respectively)." (PMID 32605217, 2020). "This opens up the possibility of combining anti-EGFR drugs with other target therapies according to each tumor’s molecular characterization, which should become progressively more common in the era of personalized medicine." (PMID 33153004, 2020). "EGFR is reported to be overexpressed in more than 90% of HNSCC and is an independent prognostic indicator which is associated with increased tumor size, shorter progression-free survival, and decreased overall survival." (PMID 33456497, 2020). "Taken together, cetuximab targeting EGFR on HNSCC cells induces potent antibody-dependent cell-mediated cytotoxicity that further augments anti-tumor effect when combined with chemotherapy." (PMID 32974098, 2020). "For example, a method of coupling either anti-EGFR or anti-Her2 monoclonal antibodies to IFN-β can result in tumor regression in tumor-bearing mice." (PMID 32571374, 2020). "Here, we report on large-scale RNAi-based screens to identify potential tumor suppressor genes that interact with known cancer-drivers: the Epidermal Growth Factor Receptor and the Hippo pathway transcriptional cofactor Yorkie." (PMID 32737065, 2020). "It appears that tumour cells use EVs as a mechanism to transfer EGFR across a gradient, from cells with high EGFR to cells with lower EGFR expression." (PMID 33143170, 2020). "As the EGFR-driven pro-survival pathway is vital to tumour progression, we evaluated the effect of DPBA on EGFR downstream signalling pathway." (PMID 33033232, 2020). "However, challenging data haverecently been demonstrated that the primary tumor test at a single site insynchronic metastatic colorectal disease can result in an incomplete profile of theKRAS mutation and, consequently, an incorrect choice of the use of EGFR inhibitorsas treatment." (PMID 33331426, 2020). "It is interesting to note that studies on the inhibition of EGFR along with c-Met have shown improved anti-tumor activity and re-sensitization of cells to EGFR targeted therapies." (PMID 35047986, 2020). "Immunostaining of invasive cell markers showed lower CD31 and EGFR expression in DCX NLS2-mut tumor." (PMID 32050972, 2020). "Amplified or mutant EGFR can lead to tumour formation due to increased cell proliferation, growth, migration and survival signals." (PMID 33143170, 2020). "Given that this miRNA has also been found to function as a tumor suppressor in the context of HCC progression through its ability to target EGFR 27, we selected it for further validation." (PMID 32742459, 2020).